CUL4B (cullin 4B)
Diseases named in the same sentence as CUL4B in open-access papers (continued):
Sharing a sentence is not in itself a finding about the gene and the disease.
cancer (49 papers, 2012 to 2025). A tumor composed of atypical neoplastic, often pleomorphic cells that invade other tissues. "CUL4B has been shown to participate in several cancer-associated processes including chemoresistance." (PMID 33869025, 2021). "Our study elucidated the dynamic role of CUL4B in the repair of radiation-induced intestinal damage and uncovered novel molecular mechanisms underlying the repair process, suggesting a potential therapeutic strategy of intestinal damage after radiation therapy for cancers." (PMID 38689033, 2024). "In recent years, CUL4B has been reported to be up-regulated in a variety of tumors and involved in cancer proliferation and progression, acting as a tumor enhancer." (PMID 40203790, 2025). "Recent studies have highlighted CUL4B's overexpression in several malignancies, including tumors of the colon, stomach, liver, and lung, suggesting its involvement in cancer progression." (PMID 40203790, 2025). "In many types of cancer, CUL4B functions as an oncogene to promote cancer growth, metastasis and drug resistance." (PMID 39695153, 2024). "While the roles of CUL4B in cancer progression and some developmental processes like adipogenesis, osteogenesis, and spermatogenesis have been studied, the mechanisms underlying the neurological disorders in patients with CUL4B mutations are poorly understood." (PMID 38331954, 2024). "Our data further confirmed the important role of CUL4B in cancer and support the oncogenic role of CUL4B in PM." (PMID 37686215, 2023). "A better understanding of the mechanisms through which CUL4B regulates TGF-β signaling in PM will better elucidate its oncogenic role in cancer." (PMID 37686215, 2023). "Although accumulating evidence indicates that CUL4B exerts biological functions in various cancers, how it contributes to skeletal development and the biological properties of MSCs, as well as its role in osteogenesis, is still poorly defined." (PMID 35784474, 2022). "By additionally comparing normal colorectal tissues and CRC tissues, it was also found that the expression of CUL4B was significantly higher in the cancer tissues." (PMID 36385733, 2022). "IL-6 secreted from CUL4B-dificient MDSCs enhances the stem cell-like properties in cancer cells through IL-6/STAT3 pathway." (PMID 36439186, 2022). "Previously, we showed that the constitutive knockdown of CUL4B inhibits the proliferation of a variety of cancer cells and contributes to cancer stemness in colorectal cancer and bladder cancer." (PMID 35784474, 2022). "CUL4B has been shown to be upregulated and promotes progression and chemoresistance in several cancer types." (PMID 33869025, 2021). "Studies in mice using either overexpression or silencing approaches indicate that both CUL4A and CUL4B play a tumor-promoting role in many cancer types including lung, breast, colon, and hepatocellular carcinomas." (PMID 34604860, 2021). "These analyses show that SIRT1 and CUL4B have similar expression trends in a variety of cancers, further supporting the idea that the SIRT1/CRL4B complex plays key roles in cancer as an organic whole." (PMID 34163012, 2021). "In summary, our analyses show that SIRT1 and CUL4B are upregulated in multiple carcinomas and are potential cancer biomarkers." (PMID 34163012, 2021). "In cancer cells, Cul4a and Cul4b have been shown to regulate proliferation, DNA damage and repair, cell cycle progression, DNA methylation and histone acetylation, as well as cell signaling." (PMID 33524014, 2021). "Recently, researchers found that CUL4B has a certain relationship with cancer development and progression including PCA." (PMID 34338146, 2021).
cancer (continued). "Next, we used Gene Expression Profiling Interactive Analysis to analyze SIRT1 and CUL4B expression profiles in The Cancer Genome Atlas tumor samples and corresponding normal tissues." (PMID 34163012, 2021). "As cancer stem cells have been considered as seeds for tumor growth and metastasis, we further evaluated the effect of CUL4B expression on metastatic capacity of PDOs." (PMID 32054830, 2020). "As expected, downregulation of miR34a was observed in 61% (23/38) of tumor tissues, while upregulation of CUL4B was observed in 68% (26/38) of cancer tissues." (PMID 32054830, 2020). "Collectively, our findings demonstrate that CUL4B functions to repress miR34a in maintaining cancer stemness in CRC and provides a potential therapeutic target." (PMID 32054830, 2020). "By acting as a miR-101-3p sponge, circZFR can accelerates NSCLC progression via enhancing CUL4B expression and regulating the cancer cell proliferation, invasion and migration mechanism." (PMID 33928018, 2020). "UPK3A, FAM3D, and LCN2, which participate cancer cell metabolisim, were also downregulated in all PDOs after CUL4B ablation." (PMID 32054830, 2020). "As a proto oncogene, Cul4B plays an important role in the occurrence and development of various cancers." (PMID 32622365, 2020). "Inhibition of CUL4B in cancer cell lines and patient-derived tumor organoids led to reduced sphere formation, proliferation and metastasis capacity." (PMID 32054830, 2020). "CUL4B has been found to be upregulated in various cancers, such as lung, bladder, and colon cancers, thus contributing to cell proliferation, invasion, and the metastasis of malignant tumors." (PMID 33324542, 2020). "We also selected 13 well-known cancer-related genes that were obviously reduced in at least two of three CUL4B knockdown PDOs." (PMID 32054830, 2020). "Overexpression of CUL4A or CUL4B is a very common sign in many types of cancers in which CUL4A or CUL4B proteins conservatively interacts with DDB1 to recruit other proteins such as RBXs and DACFs, assembling CRL4 E3 ligases 14-19." (PMID 32140073, 2020). "The CUL4B mRNA level was significantly higher in cancer tissues than that of benign prostatic tissues." (PMID 30872583, 2019). "Cul4b plays an important role in the EMT of cancer cells both in vitro and in vivo, and these studies also supported the important roles of Cul4b in primitive streak development." (PMID 31260508, 2019). "We then performed parallel experiments, looking at the role CUL4B in mediating the effects of NCBP1 on cancer cell migration." (PMID 31448526, 2019). "The exact mechanism involved in NCBP1/‐3‐mediated metabolism of CUL4B mRNA and exploring this axis as an avenue for the development of new cancer therapeutics will be the subject of our further studies." (PMID 31448526, 2019). "In this study, we show that the H2AK119ub1 E3 ligase CUL4B is required for the activation of retinoic acid (RA)-inducible developmentally critical homeobox (HOX) genes in NT2/D1 embryonal carcinoma cells." (PMID 30992047, 2019). "Here, we show that the H2AK119ub1 E3 ligase CUL4B is required for the activation of retinoic acid (RA)-inducible developmentally critical homeobox (HOX) genes in NT2/D1 embryonal carcinoma cells." (PMID 30992047, 2019). "CUL4B was positively stained in >90% of samples and was mainly localized in the nuclei of cancer cells." (PMID 28164432, 2017). "In this review, we aim to summarize the biological function of CUL4B in order to better understand its pathogenesis in human cancers." (PMID 28630798, 2017). "Meanwhile, CUL4B mRNA level was also higher in 12 of 15 selected paired samples of each grade cancers." (PMID 28630798, 2017). "On the other hand, CUL4B is overexpressed in a variety of cancers and is crucial for the maintenance of the malignant behaviors of cancer cells." (PMID 28164432, 2017). "For instance, more studies are apparently needed to further distinguish the functional distinction between CUL4A and CUL4B in cancer." (PMID 26460955, 2015).
cancer (continued). "Meanwhile, recent studies showed that CUL4B upregulated in some other cancers such as cervix, lung, esophagus and breast cancers, which associated with tumor invasion and lymph node metastasis." (PMID 26460955, 2015). "CUL4B possesses tumor-promoting properties and is markedly upregulated in many types of human cancers." (PMID 25945838, 2015). "In this review, the authors updated the recent understanding of the two Cullin 4 family members, Cullin 4A and Cullin 4B in human cancer and neuronal disease development." (PMID 23227454, 2012). "CUL4B has been reported to enhance the enrichment of cancer stem cells with stem cell-related characteristics, suggesting that CUL4B may be involved in the stemness of PDLSCs." (PMID 35784474, 2022). "Previous studies have indicated that CUL4B exerts biological functions in various types of cancers." (PMID 35784474, 2022). "CUL4B was reported to negatively regulate the biogenesis of miRNAs in many types of cancer cells." (PMID 35784474, 2022). "Likewise, miR-365a-3psuppresses NF-Kb, which is correlated with PDAC invasiveness, miR-300 inhibits EMT and cancer cell growth by targeting Cullin 4B (CUL4B), andmiR-202 upregulation suppresses proliferation by interfering with glycolysis." (PMID 36292753, 2022). "CUL4B possesses oncogenic properties in a variety of human cancers." (PMID 35784474, 2022). "The role of CUL4B in cancers is diverse and context-dependent." (PMID 33869025, 2021). "Previous studies have suggested the importance of both CUL4A and CUL4B in cancer." (PMID 34604860, 2021). "To investigate whether the effect of SIRT1 and CUL4B could be extended to a broader scope of cancers, we collected several carcinoma samples on which we performed tissue microarrays and immunohistochemical staining to examine SIRT1 and CUL4B expression." (PMID 34163012, 2021). "Cul4B participates in the oncogenesis and progression of several malignant tumors." (PMID 32622365, 2020). "As mentioned early, CUL4A and CUL4B are overexpressed in many cancer types 14-19." (PMID 32140073, 2020). "Specific knockdown of CUL4A, CUL4B or DDB1 markedly decreases cancer cell growth." (PMID 32140073, 2020). "Finally, we found that CUL4A downregulated P21 to promote cell cycle progression, and that CUL4B facilitated cancer cell survival by downregulating FOXO3A by accelerating the degradation of p-FOXO3A." (PMID 32587774, 2020). "Our findings provide evidence for future cancer therapy by interference with CUL4A or CUL4B." (PMID 32587774, 2020). "We found that microRNA‐194 (miR‐194) and CUL4B protein were inversely correlated in cancer specimens and demonstrated that miR‐194 could downregulate CUL4B by directly targeting its 3′‐UTR." (PMID 28164432, 2017). "CUL4B expression is markedly upregulated in various human cancers." (PMID 25945838, 2015). "CUL4A and CUL4B share extensive homology and functional redundancy, however CUL4A has drawn much more attention as a result of a large body of evidence demonstrating its association with cancer." (PMID 26460955, 2015). "More importantly, given their critical roles in tumorigenesis, the authors speculated that Cullin 4A and Cullin 4B could be potentially pursued as new targets for cancer prevention." (PMID 23227454, 2012). "Sphere formation assay, commonly used to identify cancer stem cells, was carried out and showed that the size and number of spheres were less and smaller in PDLSCs with knockdown of CUL4B, whereas were more and bigger in CUL4B overexpressed PDLSCs when comparing to the corresponding control group." (PMID 35784474, 2022). "Moreover, CUL4B is frequently overexpressed and functions importantly in cancer cells, an understanding of the mechanism by which CUL4B expression is upregulated such as by TMZ may also be invaluable for CUL4B-targeting cancer therapy." (PMID 33869025, 2021).
cancer (continued). "Although CUL4B has been shown to be associated with the progression and tumorigenesis of other cancers, there is, so far, no study assessing whether CUL4B is important for MPM progression." (PMID 33233664, 2020). "Thus, the function of CUL4B in cancer development and progression is dichotomous, which might be in part due to organ-specific actions and the different cellular contexts of tumors." (PMID 30872583, 2019). "Interestingly, the number of apoptotic cells are increased in cullin-4B-knockout mice embryos, and there are no cases of cancer susceptibility to XLMR linked to cullin-4B mutations." (PMID 31329620, 2019). "Thus, CUL4B transgenic mice may provide a useful animal model to study cancer development in the liver and broaden our knowledge of CUL4B as an oncogene." (PMID 25945838, 2015). "To confirm whether enhanced hepatocarcinogenesis in CUL4B transgenic mice was mediated by the same mechanism, we examined the expressions of p16 and pten, genes that are known to be repressed by CUL4B in some cancer cell lines, in the livers of CUL4B transgenic mice." (PMID 25945838, 2015). "Targeting DCAF5 can suppress SMARCB1-mutant cancer by stabilizing the SWI/SNF complex, underscoring the critical connection between CUL4B and the SWI/SNF complex." (PMID 40203790, 2025). "Cullin4B (CUL4B), which functions as a scaffold protein within the CUL4B-RING ubiquitin ligase complex (CRL4B), is frequently overexpressed in various cancers and exhibits oncogenic characteristics." (PMID 41392287, 2025). "We found that RUNX2, MTA1, or CUL4B depletion inhibited the proliferation of cancer cells, whereas RUNX2, MTA1, or CUL4B overexpression significantly promoted proliferation." (PMID 35534547, 2022). "The two cullin paralogs CUL4A and CUL4B, which form the CRL4 ligase scaffold, were depleted in cancer cells by small interfering RNA followed by analysis of the cellular and biochemical responses to ICLs elicited upon cisplatin or MMC treatment." (PMID 31690264, 2019). "Cullin 4B (CUL4B), a scaffold protein that assembles CRL4B ubiquitin ligase complexes, is overexpressed in many types of cancers and represses many tumor suppressors through epigenetic mechanisms." (PMID 28164432, 2017). "High‐throughput qPCR analyses of cancer‐related miRNAs in CUL4B knockdown A549 and control cells showed that much more miRNAs were upregulated (≥ twofold) than those that were downregulated in CUL4B knockdown cells, suggesting that CUL4B may primarily function to repress the biogenesis of miRNAs." (PMID 28164432, 2017). "Collectively, these results identify CRL4B as an essential E3 ligase in targeting the proteasomal degradation of HUWE1 in response to DNA damage, and provide a potential strategy for cancer therapy by targeting HUWE1 and the CUL4B E3 ligase." (PMID 25883150, 2015). "In our study, we found that the depletion or the inactivation of CUL4B resulted in the accumulation of HUWE1, and thereby accelerated the degradation of its substrate, MCL-1, rendering cancer cells sensitive to DNA damage agents." (PMID 25883150, 2015). "Our results indicated that CUL4B might influence the immune microenvironment of LUAD tissue, further affecting cancer progression." (PMID 38075690, 2023). "Therefore, further investigations are needed to characterize the mutual interactions of CUL4B and RUNX2 in cancers including miR-320c2 and miR-372-3p/373-3p." (PMID 35784474, 2022). "Cullin 4B (CUL4B), which assembles the CUL4B-RING ubiquitin ligase (CRL4B) complex, is involved in regulating a variety of developmental and physiological processes including the skeletal development and stemness of cancer stem cells." (PMID 35784474, 2022). "Cullin 4B (CUL4B), which is a scaffold protein of Cullin 4B-RING E3 ligase complex (CRL4B), acts as a negative regulator of MDSCs functions through several epigenetic mechanisms in various cancers." (PMID 36439186, 2022).
cancer (continued). "We demonstrated that CUL4B is a new regulator of RUNX2 for osteogenic differentiation in PDLSCs, but the relationship between CUL4B and RUNX2 in cancers remains unknown." (PMID 35784474, 2022). "Moreover, fluorescence‐activated cell sorting (FACS) analysis results showed that the populations of cells positive for the biomarkers of cancer stem cells, CD44, CD133, and ALDH, were significantly increased among cells overexpressing CUL4B." (PMID 34026424, 2021).